TNF (tumor necrosis factor)
Diseases named in the same sentence as TNF in open-access papers (continued):
Sharing a sentence is not in itself a finding about the gene and the disease.
sarcoma (continued). "Tumor necrosis factor alpha (TNFα) has been examined both as an additive to HILP with melphalan in sarcoma surgery, and also its effects on the formation of cytokines such as interleukin 6 and interleukin 8, the latter being more pronounced when TNFα was added for therapeutic purposes." (PMID 23865420, 2013). "For instance, in sarcoma, breast and leukemia cancer cells, activation of NFκB by TNFα leads to inhibition of autophagy as a result of mTOR pathway activation, whereas NFκB activation during the recovery period from heat shock has been shown to activate autophagy and promote survival." (PMID 23056618, 2012). "Furthermore, PF-4var but not PF-4 is produced constitutively by smooth muscle cells and by sarcoma cells after induction with cytokines, such as IL-1β and TNF-α, indicating that the regulated expression of these two PF-4 variants is different." (PMID 22384011, 2012). "Here we tested the ability of TNF-α to directly induce apoptosis of sarcoma cells." (PMID 22719951, 2012). "In this study, we examined the efficacy of Doxil® in a TNF-based ILP in sarcoma-bearing rats." (PMID 15208623, 2004). "Therefore, it was shown that the addition of TNFα can modulate the activity of doxorubicin and lead to a significant increase in its content in the tumor tissue in models of sarcoma, as well as the effective regression of fibrosarcoma BN175 and osteosarcoma ROS-1." (PMID 34885171, 2021). "Therefore, we investigated whether combination of Nutlin-3a and TNF-α in sarcoma cells interferes with the NF-κB-activity, which might explain the observed potentiation of TNF-α-induced cell death in the presence of Nutlin-3a." (PMID 22719951, 2012). "These ROR1 CAR-T cells were effective against sarcoma cells as evidenced by the synthesis of high levels of IFN-γ, TNF-α, and IL-13 in cocultures with sarcoma cell lines and the ability to reduce the tumor growth in a murine osteosarcoma xenograft model." (PMID 36873868, 2023). "The regulation of immune response in sarcoma patients was also studied by measuring several cytokines (IFN-γ, TNF-α, IL-17A, and TGF-β1) produced by Con-A-stimulated T cells." (PMID 36005179, 2022). "This study aimed to investigate the level of CD4+ T cells and forkhead box protein P3+ (FoxP3+) Treg cells, as well as T-cell-related-cytokines such as TNF-α, IFN-γ, IL-17A, and TGF-β1 in the peripheral blood of sarcoma patients." (PMID 36005179, 2022). "The level of TNF-α (p = 0.004) and IFN-γ (p = 0.010) in the Con-A-stimulated PBL culture supernatant from sarcoma patients was significantly lower than in normal controls." (PMID 36005179, 2022). "A marked reduction in the percentage of CD4+ T-cells (p = 0.037) and levels of TNF-α (p = 0.004) and IFN-γ (0.010) was observed in sarcoma patients." (PMID 36005179, 2022). "Although doxorubicin has been used for decades, it was recently replaced by TNFα + melphalan, which is now the standard therapy in ILP for sarcomas." (PMID 34834504, 2021). "Virus-infected sarcoma cells were shown to induce increased secretion of perforin, granzyme B, IFN-γ, TNF-α, granulysin, and sFasL in NK cells." (PMID 33322371, 2020). "Tumor necrosis factor α and melphalan (TNF-ILP) have benefited patients with locally advanced primary and recurrent extremity sarcoma in multimodal treatments." (PMID 33316779, 2020). "In sarcoma and prostatic adenocarcinoma, CAFs secrete TGF-β, IL-6 and tumor necrosis factor-alpha (TNF-α) that activate YAP1/TAZ and NFκB signaling in tumor cells, resulting in inhibition of tumor cell proliferation." (PMID 33114328, 2020).
sarcoma (continued). "A multi-institutional case series of patients with locally advanced sarcomas, considered to be irresectable with limb-conserving surgery and adjuvant radiotherapy, which were treated using ILP with TNFα reported a limb salvage rate of 84%." (PMID 29988594, 2018). "IGF1R and ROR1 CAR T cells derived from eight healthy donors using the Sleeping Beauty (SB) transposon system were cytotoxic against sarcoma cells and produced high levels of IFN-γ, TNF-α and IL-13 in an antigen-specific manner." (PMID 26173023, 2015). "Second, SB modified CAR T cells derived from healthy donors and sarcoma patients targeting IGF1R or ROR1 displayed a specific cytotoxicity and released predominantly IFN-γ, TNF-α and IL-13 cytokines against sarcomas in vitro." (PMID 26173023, 2015). "Mice implanted with S180 sarcoma showed a significant increase in serum AST, ALT and ALP activities, liver MDA level, decrease in serum WBC, TP, ALB, A/G, TNF-α and IFN-γ, and liver GSH, SOD, CAT, GSH-Px and GR activities." (PMID 22754316, 2012). "Administration of tea polyphenol increased serum TNF-α and IFN-γ levels in mice implanted with S180 sarcoma (group IV–VI)." (PMID 22754316, 2012). "In STLMS, reduced signaling from tumor necrosis factor (TNF) in the adipocytokine signaling pathway leads to elevated activation of IRS, involved in insulin sensitivity, whose expression has been related to malignant sarcoma progression." (PMID 37834179, 2023). "Furthermore, blocking the polyamine/hypusine axis augmented CD69 expression as well as IFN-γ and TNF-α production in (a) human CD8+ T cells from peripheral blood and sarcoma tumor infiltrating lymphocytes and (b) human CD8+ CAR-T cells." (PMID 37581943, 2023). "The reduced levels of TNF-α and IFN-γ in sarcoma patients observed in this study suggest that synergistic effects between these two cytokines are also reduced, which may support angiogenesis and tumor progression in these patients." (PMID 36005179, 2022). "In models of cancer cachexia, e.g., mice or rats with methylcholanthrene-induced sarcoma (MCG-101) or in LLC tumor bearing mice, skeletal muscle wasting was alleviated through the blockade of the apex pro-inflammatory cytokine TNF-α through administration of anti-TNF antibodies." (PMID 33329046, 2020). "To evaluate the possibility of harnessing RIPK1's cytotoxic and immunogenic potential during ILP‐based and TNF‐mediated treatments in combination with SM, we employed a syngeneic, immune‐competent rat model of ILP‐TNF/Mel using the syngeneic BN175 sarcoma cell line in Brown Norway rats." (PMID 32419365, 2020). "In this study, we have observed that the atrophic muscles in sarcoma-bearing mice feature the upregulated expression of both Notch genes and TNF-α, while the expression of anti-inflammation factor Klotho was downregulated." (PMID 27378829, 2016). "Role of TNF is particularly interesting because TNF, as its name suggests, has a necrotizing anti-tumor activity in MCA sarcoma model in mice that was reproduced with recombinant human TNF and also because these anti-sarcoma effects are used clinically in the isolated limb perfusion setting." (PMID 27148266, 2016). "Interestingly, TNF-α and IFN-γ were shown to affect IGF-IR promoter activity and decrease IGF-IR protein levels in human sarcoma cell lines." (PMID 22235273, 2012). "In the present study, we demonstrated that ILP treatment with Doxil® combined with TNF in sarcoma-bearing rats does not provide a useful alternative to free conventional doxorubicin." (PMID 15208623, 2004).
sarcoma (continued). "However, we observed that all four human sarcoma cell lines are not sensitive to TNFα-induced cell death." (PMID 27014915, 2016). "Patients with sarcoma of the extremity who have a good performance status may easily tolerate a protracted course of adjuvant RT following LSS, even if induction chemotherapy or tumor-necrosis factor via isolated limb perfusion had been primarily administered." (PMID 20224682, 2010). "However, Doxil® failed to induce any response in sarcoma-bearing rats, even when applied in combination with TNF." (PMID 15208623, 2004). "The concentration of other plasma cytokines, namely, TNF-α, IFN-γ, and IL-17A in sarcoma patients and normal controls, could not be determined as these cytokines were lower than the detection limit of the ELISA kits." (PMID 36005179, 2022).
bipolar disorder (81 papers, 2013 to 2026). A disorder of the brain that causes unusual shifts in mood, energy, activity levels and the ability to carry out day-to-day tasks. "Further, in bipolar disorder, a panel of proinflammatory cytokines including TNFα was associated with loss of frontal white matter integrity." (PMID 34067023, 2021). "CMV reactivation induces proinflammatory cytokines (e.g., TNF-α) associated with induction of neurotoxic metabolites and the presence of mood states in bipolar disorder (BD)." (PMID 26075105, 2015). "Increased serum inflammatory biomarkers, including COX-2, arachidonic acid, IL-6, and tumor necrosis factor-alpha, have been observed in patients with bipolar disorder." (PMID 41205479, 2025). "Abnormal levels of cytokines, including TNF-α, IL-8, and IL-10, are significantly associated with IBS and bipolar disorder symptoms, indicating that IBS and bipolar disorder share similar pathophysiological mechanisms." (PMID 38352653, 2024). "In bipolar disorder, there are several increased inflammatory markers including tumor necrosis factor-α (TNFα), interleukin (IL)-1β, IL-6, IL-4, and IL-10." (PMID 36504683, 2022). "Meta-analyses have shown higher levels of pro-inflammatory and anti-inflammatory cytokines, TNF-α, IL-1β, IL-6, IL-4, and IL-10 in patients with bipolar disorder compared to controls at baseline." (PMID 36704001, 2022). "Ex vivo studies using peripheral blood monocytes from patients with bipolar disorder have also shown that lithium reduces expression of inflammatory genes (IL-6, TNF, CXCL2) and decreases IL-6 and IL-1β production." (PMID 36704001, 2022). "It should however be noted that for other biomarkers of dissociation, such as levels of tumor necrosis factor alpha, findings in bipolar disorder are in the opposite direction." (PMID 35722564, 2022). "In contrast, we found significantly elevated TNF-alpha levels in the hypomania/mania youth subgroup compared to healthy controls." (PMID 36032249, 2022). "Regarding later stages of bipolar disorder, recent studies have reported higher levels of TNF-alpha and IL-6 in late stages of bipolar disorder." (PMID 30555363, 2018). "A meta-analysis of 30 studies that included 1351 individuals with bipolar disorder and 1248 controls found that plasma/sera levels were elevated for IL-6, TNF-α, soluble IL-2 receptor, IL-4, IL-10, IL-1 receptor antagonist, and soluble TNF receptor-1." (PMID 29803226, 2018). "In persons who have MDD and bipolar disorder, for instance, elevated proinflammatory cytokines, including interleukin-6 (IL-6) and tumor necrosis factor-alpha (TNF-α), have been detected, suggesting that gut-derived inflammation has a part to play in mental health conditions." (PMID 40255763, 2025). "Moreover, TNF-α inhibitors have been explored as adjunctive treatments in bipolar disorder, where infliximab showed benefits on depressive symptoms, cognitive function, and neuroinflammatory markers." (PMID 40943274, 2025). "Eosinophil number, and in particular eosinophil lymphocyte ratio has been considered as a marker of alcohol use in patients with bipolar disorder may relate to increased IL-5 and TNF levels, and production and release of eosinophils from bone marrow." (PMID 38545104, 2024). "Additionally, the levels of IL-6, IL-8, TNF-α, and IL-4 were found to increase during the acute manic phase of bipolar disorder." (PMID 38807424, 2024). "Taking together the evidence presented above, we propose that the role of TNF‐α elevation in patients with bipolar disorder may be secondary, or even compensatory, to the onset of the manic phase." (PMID 34590391, 2022). "Patients with bipolar disorder have elevated peripheral levels of IL-6 and TNF." (PMID 34610039, 2021). "The TNF-alpha level was found to have a negative correlation with cognitive function in bipolar disorder and was associated with impaired executive functioning in inhibitory control and motor programming among bipolar patients." (PMID 32000805, 2020).
bipolar disorder (continued). "Beside of various kinds of inflammatory disorders caused by unregulated production of TNF-α, it has been demonstrated that the increased TNF-α serum levels may augment manic and depressive episodes in bipolar disorders." (PMID 31531059, 2019). "In addition, some systematic review studies have suggested the possibility of an alteration in several inflammatory cytokines, including TNF-α and IL-6, among patients with bipolar disorder." (PMID 30114239, 2018). "Most significantly, a combination of hsCRP/IL-6, BDNF/TNF-α and sTNFR1 may offer the potential to differentiate people with bipolar disorder from matched controls specific to bipolar mood phase." (PMID 30113291, 2018). "A recent preliminary fMRI study of pediatric bipolar disorder may suggest a mechanism whereby alterations in TNF-α related processes could impact some of the symptoms in BD-I." (PMID 26075105, 2015). "In the later stages of bipolar disorder, an imbalance between inflammatory cytokines (especially TNF-alpha), mediators of oxidative stress, and BDNF persists even between episodes and is associated with metabolic disruption, progression of structural brain changes, and neurocognitive decline." (PMID 25202283, 2014). "Furthermore, studies have identified TNF-α as an important biomarker of progression of bipolar disorder, with a significant increase in patients within a minimum of 10 years of diagnosis when compared to bipolar patients in the first episode of mood and patients treated with mood stabilizers." (PMID 37274848, 2022). "Tumor necrosis factor‐α (TNF‐α) inhibitors have recently attracted interest as potential therapeutic compounds for treating depressive symptoms, but the risk for triggering mood switches in patients with or without bipolar disorders remains controversial." (PMID 34590391, 2022). "Our study indicated the distinct effects of major affective disorder diagnosis and suicide symptom severity on inhibitory control function and CRP and TNF-α levels." (PMID 39283831, 2024). "Serum levels of IL-6, IL-10, TNF-α, and MDA were also improved in patients with bipolar disorder treated for 8 weeks with a specific mix of lactic probiotics." (PMID 37764004, 2023). "Curiously, interventions at TNF/TNFR1 signalling using anti-TNF (infliximab) and pentoxifylline have been proposed to treat mood disorders such as depressive and bipolar disorders." (PMID 37018799, 2023). "Meta-analyses with three or more studies were performed for BDNF, IL-4, TNF-α and IFN-γ in patients with mania and BDNF for bipolar depression." (PMID 30113291, 2018). "BDNF is significantly decreased in both mania and bipolar depression, whereas TNF-α is raised in mania and bipolar depression, and neither are significantly different from levels in controls in euthymia." (PMID 30113291, 2018). "However, a study did show that TNFα was increased in lithium-treated bipolar disorder patients compared to non-medicated patients and healthy controls." (PMID 36504683, 2022). "Increased inflammatory biomarkers such as tumor necrosis factor-alpha (TNF)-α, IL-6, cyclooxygenase (COX)-2, and arachidonic acid (AA) were identified in bipolar disorder patients compared to healthy controls without mental illnesses; however, IL-10 and IL-33 levels remained unchanged." (PMID 35224555, 2022). "Research has indicated that individuals diagnosed with bipolar disorder (BD) might experience alterations in their olfaction or levels of serum tumor necrosis factor-α (TNF-α), but no studies have investigated olfactory function and serum TNF-α in BD patients simultaneously." (PMID 38651009, 2024).